MAP10 (microtubule associated protein 10)
Description:
Microtubule-associated protein (MAP) that plays a role in the regulation of cell division; promotes microtubule stability and participates in the organization of the spindle midzone and normal progress of cytokinesis.
Synonyms: KIAA1383; MTR120
Tractability: No criterion of Open Targets' tractability assessment is met for any kind of drug.
Gene: Protein-coding gene on chromosome 1 (232,805,416 to 232,809,929, forward strand). Ensembl gene ENSG00000212916.
Subcellular location: Cytoplasm, cytoskeleton; Cytoplasm, cytoskeleton, spindle pole; Cytoplasm, cytoskeleton, microtubule organizing center, centrosome; Midbody
Gene Ontology:
Molecular function: microtubule binding
Biological process: cytoplasmic microtubule organization; mitotic spindle midzone assembly; positive regulation of cytokinesis; regulation of microtubule-based process; microtubule cytoskeleton organization
Cellular component: centrosome; cytoplasmic microtubule; midbody; mitotic spindle midzone; mitotic spindle pole; cytoskeleton; spindle pole
Genetic constraint (gnomAD): Loss-of-function variants: 12 observed, 9.52 expected, observed/expected ratio (o/e) 1.26, 90% interval 0.8 to 1.85. That is too few expected variants to judge how well the gene tolerates losing a copy. Missense variants: 1,185 observed, 1,110.9 expected, observed/expected ratio (o/e) 1.07, 90% interval 1.02 to 1.12. Synonymous variants: 458 observed, 431.1 expected, observed/expected ratio (o/e) 1.06, 90% interval 0.98 to 1.15.
Homologues: Orthologues: chimpanzee MAP10 (99% identical), dog MAP10 (68% identical), pig MAP10 (66% identical), rabbit MAP10 (60% identical), mouse Map10 (50% identical), rat Map10 (50% identical), tropical clawed frog map10 (21% identical), zebrafish map10 (21% identical).
Diseases named in the same sentence as MAP10 in open-access papers:
MAP10 is named in the same sentence as 6 diseases in open-access papers, as found by Europe PMC text mining. Sharing a sentence is not in itself a finding about the gene and the disease. The quoted sentences say what the papers report.
diabetes (1 paper, 2024). "Interestingly, we found that OSAS.MAP10 is a protective factor for all‐cause mortality in women with diabetes in our study." (PMID 38599827, 2024). "In this study, meanwhile, we also observed higher OSAS.MAP10 levels in diabetes population." (PMID 38599827, 2024).
viral infections (1 paper, 2020). "We confirmed variants with putative driver role of MAP10, MPZL1, RPS6KA1, SETD1B, TAOK2, TMEM127, and TNFRSF1A genes, and of genes linked to viral infections (DDX3X and RSF1) and DNA repair (PAXIP1)." (PMID 32321919, 2020).
cancer (3 papers, 2024 to 2026). A tumor composed of atypical neoplastic, often pleomorphic cells that invade other tissues. "Interestingly, there was a significant correlation found for cancer mortality, when those with cardiovascular disease and those using diabetic medication were removed, the relationship between OSAS.MAP10 and cancer mortality was strengthened." (PMID 38599827, 2024).
MAP10 also shares sentences with these, for which no sentence is quoted: cardiovascular disease (1 paper); hepatocellular carcinoma (1); liver disease (1).